ATOX1 (antioxidant 1 copper chaperone)
Diseases named in the same sentence as ATOX1 in open-access papers (continued):
Sharing a sentence is not in itself a finding about the gene and the disease.
cancer (continued). "ATOX1, a key copper chaperone, has been shown to promote cell proliferation through cyclin D1 activation and facilitate cancer metastasis by accumulating at the leading edge of migrating cells." (PMID 40002764, 2025). "In contrast to the relatively well-established role of ATOX1 in the response of cancer cells to standard chemotherapy, the contribution of ATOX1 to cell susceptibility to other classes of anticancer therapeutics remains elusive." (PMID 40721800, 2025). "The overexpression of ATOX1 has been correlated with poor patient survival, while cellular localization of ATOX1 can be crucial for cancer cell fate." (PMID 40721800, 2025). "In this review, we summarize the current state of knowledge about ATOX1 in cancer focusing on its molecular aspects and potential clinical implications." (PMID 40721800, 2025). "Several copper-dependent proteins have been associated with the metastatic spread of cancer cells, and high levels of ATOX1 in cancer cells can promote their migratory and invasive properties." (PMID 40721800, 2025). "Studies have shown that copper chaperone ATOX1 is involved in the ATP7A-LOX pathway associated with tumor metastasis, and the inhibition of ATOX1 expression reduces LOX activity and the rate of cancer cell metastasis." (PMID 38200525, 2024). "It has been shown that increased ATOX1 expression leads to resistance to genotoxic drugs in a variety of cancer cells." (PMID 39482784, 2024). "It was also shown that a specific inhibitor of CCS and ATOX1 reduced cancer cell proliferation and tumor growth." (PMID 38139406, 2023). "Recent knockdown studies of Atox1 in cancer cells demonstrated that this copper chaperone is crucial for cancer cell proliferation and survival." (PMID 36299299, 2022). "We showed that those peptides that interacted with both Atox1 and MBD 3/4 of ATP7B caused preferential toxicity in cancer cells." (PMID 36299299, 2022). "To understand if ATOX1 levels in the cancer tissue relate to TM treatment outcome, we evaluated the correlation between ATOX1 expression levels and EFS in the patients." (PMID 34944703, 2021). "Because the human Cu chaperone Atox1 has been found to facilitate cancer cell migration and play an apparent role in pre-implantation mouse embryo development, we here set out to test the role of the C. elegans Atox1 homolog, CUC-1, in DTC migration." (PMID 32506305, 2020). "This hinted to a role in cancer cell migration and, indeed, upon ATOX1 silencing, wound closure was reduced." (PMID 31898157, 2020). "Recent findings indicate that Atox1 protein has transcription factor activities and plays a vital role in cell proliferation in cancer cells." (PMID 31961892, 2020). "The use of a specific inhibitor of CCS and Atox1 has been shown to reduce cancer cell proliferation and tumor growth." (PMID 33271772, 2020). "In human cells, Atox1 was found to mediate cancer cell migration by (via Cu transport) promoting extracellular, Cu-dependent, collagen-remodeling lysyl oxidase (LOX) activity." (PMID 32506305, 2020). "Interestingly, it may be the CCS and/or Atox1 absence (or downregulation, or mutation-driven loss of function) that is critically implicated in drug resistance mechanisms, being frequently observed during cancer chemotherapy." (PMID 31575544, 2019). "Remarkably, all 12 different cancers examined were shown to carry low levels of Atox1 and CCS gene expression, thereby suggesting their potential ability to develop resistance against cisplatin during malignancy clinical management." (PMID 31575544, 2019). "Our yeast two-hybrid screen identified an interaction between CPEB4 and ATOX1 which calls for further investigation of putative synergistic cancer-promoting effects between these proteins." (PMID 28425924, 2017).
cancer (continued). "For instance, cisplatin, a potent anti-cancer agent used against solid tumors of various cancers has been shown to bind to both Atox1 and ATP7B, perhaps processes governing cell resistance against this drug." (PMID 29063292, 2017). "Changing levels of Atox1 were shown to modulate response to cancer therapies, contribute to inflammatory response, and protect cells against various oxidative stresses." (PMID 27472369, 2016). "ATOX1 holds potential as a new target for RNAi-based cancer therapy of NSCLC targeting copper metabolism." (PMID 23624903, 2013). "The findings of the present study shed light on the study of ATOX1 as a new target for RNAi-based NSCLC cancer therapy targeting copper metabolism." (PMID 23624903, 2013). "Moreover, the prognostic value of ATOX1 expression for the clinical outcome of cancer patients needs to be clarified." (PMID 40721800, 2025). "Notably, these cancer cells presented increased levels of ATOX1 after pressure selection with a high dose of gemcitabine, while ATOX1 knockdown in drug-resistant cells sensitized them to gemcitabine." (PMID 40721800, 2025). "A shift in the subcellular localization of ATOX1 to the nucleus can contribute to cancer spread." (PMID 40721800, 2025). "Additionally, recent knockdown studies of Atox1 in cancer cells demonstrated that this copper chaperone is crucial for cancer cell proliferation and survival." (PMID 41463392, 2025). "Copper homeostasis is critical for the efficacy of platinum-based chemotherapy, and ATOX1 may play a key role in the development of drug resistance in cancer cells." (PMID 40721800, 2025). "As autophagy can have a dual role in cancer cells by either a protumorigenic or a cell death-inducing process, the further role of ATOX1 in this respect may be crucial from a therapeutic point of view." (PMID 40721800, 2025). "In particular, the recent discovery of the mechanism of ‘copper death’ (cuproptosis) has highlighted new opportunities for targeting copper homeostasis to induce cancer-specific death, providing a more robust theoretical basis for targeting copper metabolism through ATOX1." (PMID 40940984, 2025). "Considering the extensive role of ATOX1 in distinct key functions of cancer cells, the ATOX1 transcript and/or protein levels might be considered to have prognostic value." (PMID 40721800, 2025). "Indeed, ATOX1 levels are frequently increased in cancer as demonstrated in multiple studies and supported by data available in GEPIA." (PMID 40721800, 2025). "As ATOX1 is a crucial intracellular copper chaperone, ATOX1 inhibition in cancer cells increases total cellular copper and ROS levels, which is associated with decreased SOD1 activity and ATP synthesis as well as lower NADPH and GSH levels, leading to impaired ROS clearance." (PMID 40721800, 2025). "Consequently, knockout or blockade of ATOX1 rendered cancers sensitive to gemcitabine in transplanted cancer mouse models." (PMID 39430913, 2024). "Additionally, the copper molecular chaperone ATOX1 has been proven to play a role in the migration of BC cells, and migration is a crucial step in cancer invasion and metastasis." (PMID 39482784, 2024). "ATOX1 may also stimulate cyclin D1 in a Cu-dependent manner, potentially contributing to cancer cell proliferation and angiogenesis." (PMID 38139406, 2023). "Consistent with our findings, others have also reported nuclear Atox1 in various cancers." (PMID 36139494, 2022). "The ATOX1 correlation in TNBC suggests that, here, ATOX1-dependent processes play a crucial role in cancer progression (such as metastasis), and therefore copper depletion with TM may have a beneficial effect." (PMID 34944703, 2021). "Since cancer metastasis consists of a cascade of processes that depends sensitively on cell migration this implies that ATOX1 may be important for processes facilitating metastasis." (PMID 31898157, 2020). "For prognostic purposes, nuclear Atox1 expression was scored only in the cancer epithelium." (PMID 31961892, 2020).
cancer (continued). "As different subtypes may be dominated by different oncogenic pathways, it is possible that ATOX1 acts in several cancer-promoting molecular paths leading to patient death." (PMID 31898157, 2020). "The Atox1 protein is increased in many types of cancer tissues." (PMID 33271772, 2020). "Furthermore, 6 out of 12 (50%) cancers are characterized by detectably downregulated Atox1 and/or CCS gene activities." (PMID 31575544, 2019). "Indeed, several types of different human cancers analyzed via employment of the TCGA bioinformatics platform are characterized by strikingly diminished levels of Atox1 and CCS gene expression compared to control." (PMID 31575544, 2019). "However, unprecedented findings have suggested that the Cu chaperone ATOX1 has new activities connected to cancer." (PMID 28425924, 2017). "We hypothesized that ATOX1 may play a role in copper-regulated proliferation of NSCLC cells, and ATOX1 may be a new target for RNAi-based cancer therapy targeting copper metabolism." (PMID 23624903, 2013). "Additionally, ATOX1 may impact the drug response and resistance of cancer cells by influencing detoxification mechanisms as demonstrated for platinum-based therapies." (PMID 40721800, 2025). "From these genes, we identified ATOX1, which is known to play a functional role as antioxidant against superoxide and hydrogen peroxide and may play a significant role in cancer carcinogenesis." (PMID 38642129, 2024). "However, the larger sample size for the TNBC subgroup implies that ATOX1 may be a predictive biomarker for TM in this cancer subtype." (PMID 34944703, 2021). "Thus, the function and regulation of Atox1 and its role in cancer have attracted much attention." (PMID 31961892, 2020). "Antioxidant 1 (ATOX1) copper chaperone and RhoA/Rho kinase 1 (ROCK1) are novel anti-tumour targets in cancers." (PMID 40940984, 2025). "Therefore, the disruption of ATOX1-mediated processes could be beneficial for the efficacy of anticancer therapies, although this possibility should be treated with caution because of the dual role of copper in cancer." (PMID 40721800, 2025). "Cancer cells accumulate copper, and studies have shown that CRIP2 can bind to the antioxidant 1 copper chaperone (ATOX1)." (PMID 40118853, 2025). "To substantiate the potential role of ATOX1 in cancer, we retrieved expression data from GEPIA for a broad panel of cancer types and compared the expression of ATOX1 in cancer cells with its level in normal tissues." (PMID 40721800, 2025). "A recent study also demonstrated that small molecules that inhibit the human copper trafficking proteins Atox1 and CCS significantly reduce proliferation of cancer cells, suggesting copper chaperones as new targets for the development of anticancer therapies." (PMID 29320492, 2018). "While the role of ATOX1 has not been investigated in this context, the cancer type-specific contribution of ATOX1-related partners to cancer cell migratory and invasive potential points to a presumably complex role of ATOX1 in these processes." (PMID 40721800, 2025). "Several candidates identified in our experiment, either in CuCl2-or CuCl2 and LA-treated groups, are directly involved in cancerogenesis (such as MEMO1, ATOX1, L1CAM, RABGGTA, MAP2K7 and others, and may be of potential interest for anti-cancer research." (PMID 39290994, 2024). "Interestingly, several studies have reported that cuproptosis–related genes (CRGs), such as antioxidant 1 copper chaperone (ATOX1), can impact cancer progression." (PMID 37886979, 2023). "Here, we provided evidence and expanded on previous results by showing that peptides targeting Atox1 and/or ATP7B MBD3/4 can preferentially elicit cancer cell death when administered in the μM range, owing to an increase in copper concentration within the cell." (PMID 36299299, 2022).
cancer (continued). "While many mechanisms have been proposed for Pt-drug transport, the high-affinity copper transporter (hCtr1), Cu chaperone (Atox1), and Cu exporters (ATP7A and ATP7B) are also involved in cDDP transport, highlighting Cu homeostasis regulation in Pt-based cancer therapy." (PMID 34201235, 2021). "Therefore, we investigated the effect of endogenous Atox1 on the expression of NADPH oxidase, a major source of ROS in cancer by measuring expression of p47 phox, a subunit of NADPH oxidase as a surrogate for ROS levels." (PMID 31961892, 2020). "In accordance with this, it was recently shown that small molecules that inhibited cellular Cu transport, by specific targeting of CCS and ATOX1, acted as a selective approach to reducing proliferation of cancer cells but not normal cells." (PMID 28425924, 2017). "In ER-negative tumors, other pathways (not dependent on ATOX1 levels) may instead define cancer progression." (PMID 31898157, 2020). "Strikingly, regarding their differential expression in 12 out of the 14 cancers analyzed, neither Atox1 nor CCS genes are found significantly upregulated, with the comparably strongest expression levels being respectively measured in UCEC and BRCA malignancies." (PMID 31575544, 2019). "ATOX1 may be mediating the delivery of Cu to Cu-binding proteins located in the lamellipodia, such as MEMO (Mediator of ErbB2-driven cell motility), which is separately known to regulate cancer cell migration." (PMID 33912613, 2018). "It has not been determined if ATOX1 plays a direct role in Cu-dependent cancer metastasis." (PMID 33912613, 2018). "In addition, treatment with activin A, a member of the transforming growth factor beta (TGF-β) family involved in cancer cell migration and epithelial-to-mesenchymal transition, promoted the nuclear translocation of ATOX1 in both nonmetastatic and metastatic cell lines." (PMID 40721800, 2025).
tumor (32 papers, 2009 to 2025). "Elevated expression of ATOX1 has been associated with tolerance to cisplatin in several tumor cell lines." (PMID 32155756, 2020). "It has also been reported that ATOX1 transcriptionally regulates SOD3 expression in diverse types of cells, including tumor-associated macrophages, suggesting that ATOX1 may play a role in tumor progression." (PMID 40721800, 2025). "We specifically sought to explore whether there was an association between ATOX1 expression in the primary tumor (before TM treatment) and outcome in patients receiving TM as a therapeutic strategy." (PMID 34944703, 2021). "Through its regulation of copper transport and metabolism, ATOX1 reduces oxidative stress levels, thereby inhibiting tumor cell proliferation." (PMID 40406488, 2025). "Tumour cells, due to their rapid growth and proliferation, require much more copper than normal cells, which makes it highly likely that ATOX1 will play a facilitating role in copper metabolism in tumour cells." (PMID 40940984, 2025). "ATOX1 has been implicated in regulating the ATP7A-LOX axis, a key pathway involved in tumor cell migration and metastasis." (PMID 40002764, 2025). "ATOX1 is involved in regulating copper levels in tumour cells through binding and transport of copper ions." (PMID 40940984, 2025). "Research suggests that modulating ATOX1 expression levels significantly impacts copper metabolism and cuproptosis mechanisms, with important implications for tumor cell growth and survival." (PMID 40406488, 2025). "Among the proteins involved in copper metabolism, ATOX1, a copper chaperone, has been identified as a critical mediator of tumor progression." (PMID 40002764, 2025). "When combined with ATOX1, copper can enhance tumor cell proliferation by upregulating Cyclin D1 expression." (PMID 39691393, 2024). "Our study identified LIPT1 as a valuable prognostic biomarker in NSCLC as it elucidates its tumor-inhibitory role through the modulation of ATOX1." (PMID 38041690, 2024). "In this regard, depletion of ATOX1 inhibits vascular smooth muscle cell migration stimulated by platelet-derived growth factor (PDGF), supporting a role for ATOX1 in vascular remodeling and tumor angiogenesis." (PMID 38139406, 2023). "At the same time, a connection between high ATOX1 expression level and survival rate in primary tumor biopsies has been found." (PMID 36296659, 2022). "The EFS for stage III patients with high tumor cytoplasmatic ATOX1 was 81% versus 25% for patients with low ATOX1 (p = 0.018)." (PMID 34944703, 2021). "ATOX1 intensity levels in the tumor cell nucleus and cytoplasm of whole tissue sections correlated for 44%, with 10 low and 31 high nuclear ATOX1 intensity cases versus 8 low and 39 high cytoplasmatic ATOX1 intensity cases." (PMID 34944703, 2021). "Classical immunohistochemistry was used to manually score ATOX1 levels in tumor cells and the staining intensities were grouped into low (intensity scores 0 and 1) and high (intensity scores 3 and 4) ATOX1 levels." (PMID 34944703, 2021). "We found that patients with high ATOX1 expression levels in their primary tumor have approximately 50% lower survival chances (median DSS decreased by a factor of 2)." (PMID 31898157, 2020). "In line with our observations, silencing ATOX1 has been reported to reduce tolerance to cisplatin in tumor cells." (PMID 32155756, 2020).